CDK4 (cyclin dependent kinase 4)
Diseases named in the same sentence as CDK4 in open-access papers (continued):
Sharing a sentence is not in itself a finding about the gene and the disease.
tumor (continued). "Senescent cells harbour vulnerabilities allowing their specific killing by various ‘senolytics’, including BCL‐2 and BCL‐xL inhibitors (venetoclax, navitoclax, A1331852...) that were observed to augment the tumour response to CDK4/6i." (PMID 36453028, 2024). "In vivo, AT7519 effectively inhibited the AM tumor growth bearing CDK4 gain + CCND1 gain, CDK4 gain + p16INK4A loss or only CDK4 gain, whereas palbociclib was effective in mouse models with CDK4 gain + CCND1 gain and CDK4 gain + p16INK4A loss." (PMID 39598629, 2024). "miR-1 acts as a tumor suppressor, promoting the inhibition of tumor growth and acting with multiple target genes, such as CDK4, TMSB4X, WASF2, TWF1, CNN3, and CORO1C which are genes involved in cell cycle and metastasis." (PMID 38813102, 2024). "Mechanistically, CDK4/6is can selectively block cell-cycle progression, leading to the inhibition of cell proliferation, tumor cell senescence, and the disruption of energy metabolism." (PMID 39593745, 2024). "Both ER‐dependent and ‐independent mechanisms modulate cell cycle checkpoints, where CDK4/6 inhibition has attained remarkable success in HR+ tumours." (PMID 38264947, 2024). "Research findings indicate that the combination of CDK4/6 inhibitors with neoadjuvant endocrine therapy can greatly enhance the inhibitory impact on tumor cells." (PMID 39247184, 2024). "MAO demonstrated G1-phase cell arrest due to reduced p21, Cyclin D, and CDK4, similar to a previous study on anthocyanins inhibiting tumor cell growth and apoptosis induction." (PMID 39605764, 2024). "A recent report showed that selective CDK4/6i induced not only tumor cell cycle arrest but also antitumor immunity." (PMID 38684839, 2024). "Oral administration of ZN-c5 at 5 mg/kg and 10 mg/kg resulted in significant inhibition of tumor growth in MCF-7 orthotopic tumor xenograft models, and ZN-c5 combined with CDK4/6 or PI3K inhibitors enhanced antitumor activity." (PMID 38339371, 2024). "The expression of HLA in CCND1-amplified tumor cells was upregulated by CDK4/6 inhibitors, which also activated the expression of retroviral elements in tumor cells treated with Abemaciclib." (PMID 39544302, 2024). "High nuclear CDK4 was observed in 41/255 (16%) and high cytoplasmic CDK4 was observed in 77/255 (31%) of tumours." (PMID 38612869, 2024). "Specifically, it was hoped the research here would show that SelK can function as a tumor enhancer by controlling the cell cycle of GB cells through the ER Stress/SKP2/β-TrCP1/CDK4 pathway." (PMID 39155374, 2024). "While CDK4/6 inhibition has been shown to effectively suppress tumor proliferation by inducing senescence in both in vitro and in vivo preclinical melanoma models, its efficacy has not been replicated in clinical trials for melanoma." (PMID 39695080, 2024). "Cyclin D1/CDK4 acts as a key effector of AKT, mediating resistance to HER2-directed therapies, and CDK4/6 inhibitors can resensitize resistant tumor cells." (PMID 39769140, 2024). "Of these, Cyclin D1 induces the transition from the G1 to S phase through complex formation with Cdk4 and Cdk, leading to tumour growth." (PMID 38612399, 2024). "Agents specifically targeting cyclin-dependent kinases 4 or 6 (cyclin-dependent kinases 4/6, CDK4/6) (palbociclib, ribociclib, etc.)have a high affinity for CDK4/6, which can lead to G1-phase cell cycle arrest and tumor growth inhibition." (PMID 38890443, 2024). "It has been reported that the combined use of BCL2, CDK4/6 inhibitors or MEK inhibitors can synergistically enhance the anti-tumor effects of MDM2 inhibitors in different types of tumors." (PMID 39215364, 2024). "CDK4/6i activates tumor cell expression of endogenous retroviral elements and increases intracellular levels of double-stranded RNA." (PMID 38684839, 2024). "In a preclinical model, at low doses, GDC-9545 promotes tumor regressions either as a single agent or combined with a CDK4/6 inhibitor in an ESR1 Y537S mutant PDX and in a wild-type ERα breast tumor model." (PMID 39767607, 2024).
tumor (continued). "More than 300 clinical trials for more than 50 tumor types investigated the antitumor activity of palbociclib, ribociclib, or abemaciclib—three small-molecule CDK4/6 inhibitors." (PMID 39598723, 2024). "It is also known that p16 is a tumor suppressor protein that acts by inhibiting the cyclin D1/CDK4 complex, favoring the survival of tumor cells." (PMID 38742684, 2024). "New selective inhibitors of cyclin-dependent kinases 4 and 6 (CDK4/6) have shown promise in various malignancies by inhibiting cell cycle progression and suppressing tumor growth." (PMID 39011477, 2024). "CDK4 phosphorylation is detected in about 80% of MPM tumours, which are therefore predicted to be responsive to CDK4/6i." (PMID 36453028, 2024). "Overall, CDK4/6i, in addition to their direct cytostatic tumour action, would greatly facilitate response of MPMs to immune checkpoint inhibitors including the newly FDA‐approved combination of nivolumab and ipilimumab." (PMID 36453028, 2024). "Firstly, we transfected RKO cells with siRNA specifically designed against exon 2 of CDK4, followed by conducting tumor cell function-related experiments." (PMID 39004679, 2024). "Despite the activation of regulatory T cells, we combined it with CDK4/6 inhibitors (Palbociclib) to enhance the immune response while reversing its immunosuppressive effects, resulting in further slowed tumor growth." (PMID 38352877, 2024). "Currently, the CDK4/6-retinoblastoma (RB) pathway is widely recognized as an important pathway involved in tumor regulation." (PMID 38890443, 2024). "AMBRA1 was recently described as a potent tumor suppressor, which regulates the stability of D-type cyclins and S phase entry, and loss of AMBRA1 has been suggested to decrease sensitivity to CDK4/6 blockade." (PMID 39617889, 2024). "Palbociclib (CDK4/6 inhibitor) as a reference drug was also assessed to validate the results, which showed a promising anti-tumor effect in HNMM-PDX harboring CDK4 amplification in our previous study." (PMID 38807144, 2024). "Our findings indicate that this compound can effectively disrupt the interactions between CCND1 and CDK4, leading to inhibition of tumor cell proliferation." (PMID 38957406, 2024). "In the Phase Ib trial in patients with advanced WDLPS or DDLPS, combining an MDM2 inhibitor with a CDK4/6 inhibitor ribociclib was demonstrated to have an initial anti-tumor effect and a controlled safety profile." (PMID 39606156, 2024). "In this review, we discuss in depth the essential role of CDK4/6is and their anticancer effects brought about by increased tumor cell immunogenicity, activation of effector T cells, induction of memory CD8+ T cells, and immunogenic cell death." (PMID 39593745, 2024). "None of those genes had significantly higher alteration prevalence post-AI or post-chemotherapy, and the post-treatment prevalence was highest in the AI+CDK4/6i cohort, reinforcing the specific and profound impact of CDK4/6i on the tumor genomic landscape." (PMID 38388477, 2024). "has confirmed that CDK4/6 inhibitors, when combined with anti-PD-1 inhibitors, significantly inhibit tumor growth and proliferation in mice, resulting in a marked increase in overall survival." (PMID 39315102, 2024). "Increased E2F transcriptional activity during tumour development is often achieved by increased expression or genomic amplification of the Cyclin D or Cyclin E genes that lead to increased CDK4/6/2 activity." (PMID 38678032, 2024). "A recent report showed that selective CDK4/6i induces not only tumor cell cycle arrest but also antitumor immunity." (PMID 38684839, 2024). "On the other hand, the onco‐suppressor pRb (RB1), the main target of CDK4, has been found to be intact in most MPMs, pointing out these tumours as paradigmatic targets for CDK4/6 inhibitors (CDK4/6i)." (PMID 36453028, 2024). "Among tumor suppressor genes, CDKN2A/p16 (p16 inhibitor of cyclinD/Cdk-4 complexes) have been found to be inactivated by mutation in more than 90% of PDACs." (PMID 38607041, 2024).
tumor (continued). "As anticipated, single agent CDK4/6 or MEK inhibitors provided a modest survival benefit reflecting slowed tumor growth whereas dual CDK4/6-MEK inhibition induced tumor regression and greatly extended survival." (PMID 39347707, 2024). "As a master tumor suppressor, P16 inhibits CDK4/6-catalyzed RB1 phosphorylation while simultaneously driving the feedforward degradation of RB1." (PMID 39351198, 2024). "Inhibition of CDK4/6 is known to enhance T cell activation, bolster tumor immunological infiltration, reinforce immunological memory, and amplify the anti-tumor immunity elicited by anti-PD-1 antibodies." (PMID 39544292, 2024). "Nevertheless, recent studies reveal that CDK4/6i treatment can elicit anti‐tumor immunity by targeting tumor cells and regulatory T cells and can also synergize with immune checkpoint inhibitors." (PMID 37854019, 2024). "Again, these data support an irreversible cell cycle exit of DPM cells upon treatment with this CDK4/6i in a model that better recapitulates in vivo tumor growth." (PMID 39011477, 2024). "We found complexity in the process of acquired resistance to CDK4/6i therapy revealed by tumor evolutionary analysis." (PMID 38503755, 2024). "Overall, tumor evolutionary analysis identified acquired genomic alterations that we attributed to acquired CDK4/6i and endocrine therapy resistance." (PMID 38503755, 2024). "By regulating key mechanisms such as the cell cycle, transcription factors, and cell apoptosis, CDK4/6 participates in the regulation of tumor occurrence and development." (PMID 38890443, 2024). "Meanwhile, CDK4/6 inhibitors substantially reduce the proliferation of regulatory T cells and encourage cytotoxic T cells to eliminate tumor cells." (PMID 38605349, 2024). "It has also demonstrated antitumor activity in ER-positive patient-derived xenograft (PDX) tumor models with ESR1 mutations and with models for cyclin-dependent kinase 4/6 (CDK4/6) inhibitor resistance." (PMID 39767607, 2024). "Our study helps shed further light on CDK4/6 inhibitor effects on the tumor immune microenvironment in the clinical setting." (PMID 38448600, 2024). "The IL‐6/STAT3 pathway involves key proteins like Bcl‐2 and Bax, crucial for tumour cell apoptosis and Cyclin D1 and CDK‐4, which contribute to tumour cell proliferation." (PMID 39495702, 2024). "In this study, it is found that CDK4/6is palbociclib (PD) or ribociclib (LEE) combined with chemotherapeutic drugs significantly inhibit SCLC tumor growth." (PMID 39136283, 2024). "Extensive preclinical data support their potential to overcome CDK4/6 inhibitor resistance, induce synthetic lethality or sensitise tumours to immune checkpoint inhibitors." (PMID 38264947, 2024). "Another study demonstrated that CDK4/6is induced a pro-inflammatory immune response in the tumor microenvironment." (PMID 39593745, 2024). "Together, these results revealed that BEZ235-induced autophagy plays a critical role in CDK4 degradation and tumor proliferation inhibition in NB xenografts." (PMID 39087955, 2024). "On the other hand, it can reduce the expression of cell cycle proteins such as Cyclins B1, Cyclins D1, CDK1, CDK2, and CDK4, preventing the transition of tumor cells from the G2 phase to the M phase and inhibiting cell proliferation." (PMID 39274982, 2024). "The successful translation of Cdk4/6 inhibitors from basic research to clinical use has brought attention to the cell cycle in tumor cells." (PMID 38701314, 2024). "Mechanistically, ATP-competitive CDK4/6 dual inhibitors such as abemaciclib, palbociclib and ribociclib, block CDK4/6, stop the phosphorylation of Rb and arrest G1 cell cycle development of tumor cells." (PMID 38409585, 2024). "Here, we use this experimentally derived NeST map as the foundation for a visible deep learning approach to understand how patterns of genetic alterations govern the tumor response to CDK4/6 inhibition." (PMID 38443662, 2024).
tumor (continued). "In agreement with the in vitro findings, the expression of NRAS, p-ERK1/2, CDK4, Cdc25A, and CydlinD1 was inhibited in tumor grafts with the treatment of DHA." (PMID 38778121, 2024). "This study enables an integrated assessment of how a tumor’s genetic profile modulates CDK4/6i resistance." (PMID 38443662, 2024). "CDK4/CDK6 have been implicated in MM cell proliferation, and their inhibition has shown promise in reducing the MM tumor burden." (PMID 39664374, 2024). "Melanocytes were predominantly found in two tumor tissues, where CDK4 subpopulation was predominantly expressed in SM and GAB2 subpopulation was predominantly expressed in PM." (PMID 38528036, 2024). "Treatment with BCA alone and in combination with EU also induced the cell cycle arrest of tumor cells in the G0/G1 phase, and the reduction in CDK4 gene expression is likely to contribute to inhibiting tumor cell growth." (PMID 39796096, 2024). "We demonstrate here that previous large-scale screens designed to identify which tumour types or genotypes are most sensitive to CDK4/6 inhibitors have misrepresented the responsive cell lines because of a reliance on metabolic proliferation assays." (PMID 38438376, 2024). "Currently, CDK4/6 inhibitors such as Palbociclib and Trilaciclib have been used in clinical settings for tumor treatment; however, their efficacy remains limited." (PMID 39004679, 2024). "The CDK4/6 inhibitors can not only target the tumor cells directly but also the tumor microenvironment, suggesting future work combining these agents with immunotherapies." (PMID 38746220, 2024). "Molecular features of the tumor before medical treatment suggested applicability of CDK4/6 inhibitor and the patient showed partial response (PR) according to Choi Criteria after 4 months treating with Palbociclib until progression occurred." (PMID 38369555, 2024). "In conclusion, our work uncovers opportunities for further treatment personalization and stresses the need for effective combination treatments to address the altered tumor genomic landscape following AI+CDK4/6i exposure." (PMID 38388477, 2024). "We demonstrated that CDK4/6 inhibitors impeded chemoresistance and inhibits tumor growth using different SCLC animal models." (PMID 39136283, 2024). "The CDK4/6-cyclinD protein complex has been found to be hyperactivated in many cancers and therefore promote tumor growth." (PMID 39088265, 2024). "Chemotherapy results in cytotoxicity and killing of tumor cells and targeted therapy with CDK4/6 antagonists prevent expansion of cells which escape cytotoxicity." (PMID 38746220, 2024). "The CDK4 inhibitor palbociclib has shown promising results in halting cell cycle progression and inhibiting tumor cell proliferation and invasion." (PMID 39590345, 2024). "Surprisingly, phospho‐CDK4 was also undetectable in two proliferative tumours expressing very low levels of CDKN2A (E7 and L14)." (PMID 36453028, 2024). "The dysregulation of CDK4/6 in tumor cells is a critical factor in sustaining tumor cell proliferation, making CDK4/6 inhibitors a focal point in inhibiting tumor growth." (PMID 38410129, 2024). "HZ1 showed strong tumor-suppressing effect with IC50 at nanomolar range and the potential to overcome resistance to CDK4/6 inhibitor, and manifested satisfactory tumor clearance in laboratory animals and patient-derived samples." (PMID 38963708, 2024). "Then, a drastic molecular alteration of the tumor as represented by emergence of dramatic E2F amplification, which is known to induce CDK4/6 independent cell-cycle entry and progression after treatment, was detected." (PMID 38369555, 2024). "The cellular senescence induced by CDK4/6is exerts diverse effects on the tumor cells with various genetic configurations." (PMID 39593745, 2024).
tumor (continued). "In summary, these results established that the MYC-degrading molecule A80.2HCl potentiates the therapeutic efficacy of CDK4/6i in inhibiting tumor growth, thereby providing an effective cancer treatment drug target for overcoming CDK4/6i resistance." (PMID 38424044, 2024). "Since it has been reported that tumor-specific CD8+ T cells treated with CDK4/6 inhibitors promote T-cell persistence and the formation of immunological memory." (PMID 38750022, 2024). "The multivariate analysis included tumour stage and CDK4, CDK6, CDK2, cyclin D1, cyclin E1, RB1 and pRB1 protein expression." (PMID 38612869, 2024). "The inhibition of cell cycle progression resulting from CDK4/6 inhibition is well described and one of the main reasons for the observed therapeutic response in RB-positive tumor cells." (PMID 39461947, 2024). "In a prospective study (NCT02866149), we assessed the efficacy of fulvestrant and everolimus in CDK4/6i pre-treated mBC patients and circulating tumor DNA (ctDNA) changes throughout therapy." (PMID 38413796, 2024). "Three CDK4/6i—palbociclib, ribociclib, and abemaciclib—share a common mechanism of action, inhibiting CDK4/6 to halt the phosphorylation of retinoblastoma protein and arrest the G1 cell cycle phase in tumor cells." (PMID 39133334, 2024). "Western blot analysis showed a significant decrease in the expression levels of MCL-1, CDK4, and phosphorylated Rb in A2058 xenograft tumor of the 5 and 10 mg/kg RC48 groups compared with the vehicle groups." (PMID 38594618, 2024). "We explore the downstream impacts of these CDK4/6 inhibitors, focusing on cell lines and patient-derived tumor samples." (PMID 38992220, 2024). "In PDX models bearing the ESR1 Y537S mutant, palazestrant inhibits tumor growth at a 3 mg/kg dose and enhances tumor shrinkage at higher doses or combined with CDK4/6 inhibitors." (PMID 39767607, 2024). "In preclinical studies, palazestrant demonstrated tumor regression in ER+ xenograft models, and CDK4/6 inhibitors enhanced its efficacy." (PMID 39767607, 2024). "We collected a research tumor biopsy and blood sample at baseline (after progression on the prior CDK4/6 inhibitor but before initiation of triplet therapy) and additional serial blood samples while on the trial." (PMID 38503755, 2024). "The pathway CDK-RB1-E2F targeted by CDK4/6 inhibitors is vital for inhibiting the proliferation of tumor cells and it is disrupted in a majority of cancers." (PMID 38215156, 2024). "The combined MEK and CDK4/6 inhibition induced tumour senescence and SASP‐driven endothelial cell activation, fostering the accumulation of CD8+ T cells and rendering tumours more responsive to PD‐1 checkpoint blockade." (PMID 39270064, 2024). "Therapeutic decisions following progression on first-line treatment with endocrine therapy and CDK4/6 inhibition should be based, whenever this is possible, on a genomic analysis of the patient’s tumor or circulating tumor DNA (ctDNA)." (PMID 38791880, 2024). "An analysis of the underlying mechanism identified a total of 21 interacting proteins implicated in tumor formation, and among these, AKT1, CDK4, GNB2, and MAPK8 were confirmed at both gene and protein levels." (PMID 39336799, 2024). "Most genomic alterations described in CDK4/6i‐resistant tumours converge on their ability to override the G1/S checkpoint." (PMID 38264947, 2024). "All tumor samples revealed positivity for CDK4, CDK6 (except in one patient), Rb, and pRb, reinforcing cell cycle deregulation." (PMID 39411551, 2024). "To do this, we carried out evolutionary analysis (tumor phylogeny, clonal dynamics) to identify acquired or enriched genomic alterations in the trial baseline sample(s) (which are post-CDK4/6i) as compared to the older, pre- CDK4/6i sample." (PMID 38503755, 2024).